GUSBP2 (GUSB pseudogene 2)
Synonyms: bA239L20.5; bA239L20.1; SMA3-L; bGLU-Lp; SMAC3L; formerly SMAC3L2; GUSBL1
Gene: Transcribed unprocessed pseudogene on chromosome 6 (26,878,572 to 26,889,198, reverse strand). Ensembl gene ENSG00000241549.
Diseases named in the same sentence as GUSBP2 in open-access papers:
GUSBP2 is named in the same sentence as 3 diseases in open-access papers, as found by Europe PMC text mining. Sharing a sentence is not in itself a finding about the gene and the disease. The quoted sentences say what the papers report.
asthma (1 paper, 2020). "Regarding GUSBP2, the associations with asthma actually has been reported in a microarray study for asthma, which showed that GUSBP2 was differentially expressed in comparison of asthmatic patients with health controls." (PMID 32948203, 2020). "To test our findings that those specific lncRNAs and mRNAs probably associated to immune/inflammatory-related genes in asthma, we selected three lncRNA/mRNAs, including KLRK1, LINC02145, GUSBP2, which exhibits differential expression before and after treatment for the qRT-PCR." (PMID 32948203, 2020). "In the present study, our network analysis disclosed GUSBP2 exhibiting correlations to these immune/inflammatory-related genes, implying it might target to these genes to participate the regulation of immune and inflammatory process in asthma." (PMID 32948203, 2020). "Subsequent network analysis based on PCC figured out several key lncRNAs probably interacted to those key asthma-related genes, i.e., LINC02145, GUSBP2." (PMID 32948203, 2020).
Crohn disease (1 paper, 2020). A gastrointestinal disorder characterized by chronic inflammation involving all layers of the intestinal wall, noncaseating granulomas affecting the intestinal wall and regional lymph nodes, and transmural fibrosis. "Indeed, GUSBP2 was found as the highest up-regulated fold change of lncRNA in CD (Crohn’s disease) patient plasma via microarray screening." (PMID 32948203, 2020).
inflammatory bowel disease (1 paper, 2020). A spectrum of small and large bowel inflammatory diseases of unknown etiology. "CD is known to us as one of inflammatory bowel diseases, which suggests the existence of strong association between GUSBP2 and inflammatory reaction." (PMID 32948203, 2020).